SALL2 (spalt like transcription factor 2)
Description:
Probable transcription factor that plays a role in eye development before, during, and after optic fissure closure.
Synonyms: Sal-2; hSal2; KIAA0360; ZNF795; COLB; p150(Sal2)
Tractability: PROTAC: UniProt records ubiquitination sites on it; ubiquitination databases record sites on it.
Gene: Protein-coding gene on chromosome 14 (21,521,080 to 21,537,216, reverse strand). Ensembl gene ENSG00000165821.
Subcellular location: Nucleus
Subcellular location (Human Protein Atlas): Vesicles; Nucleoplasm
Gene Ontology:
Molecular function: DNA-binding transcription activator activity, RNA polymerase II-specific; protein binding; RNA polymerase II transcription regulatory region sequence-specific DNA binding; DNA-binding transcription factor activity, RNA polymerase II-specific
Biological process: eye development; positive regulation of transcription by RNA polymerase II; regulation of transcription by RNA polymerase II; system development
Cellular component: nucleus
Genetic constraint (gnomAD): Loss-of-function variants: 32 observed, 59.48 expected, observed/expected ratio (o/e) 0.54, 90% interval 0.41 to 0.72. The upper end of that interval is the gene's LOEUF score, 0.72, which puts it in group 2 of 6, group 1 being the genes least tolerant of losing a copy. Missense variants: 1,201 observed, 1,322.4 expected, observed/expected ratio (o/e) 0.91, 90% interval 0.87 to 0.95. Synonymous variants: 516 observed, 533.83 expected, observed/expected ratio (o/e) 0.97, 90% interval 0.9 to 1.04.
Homologues: Orthologues: chimpanzee SALL2 (98% identical), rabbit SALL2 (91% identical), guinea pig SALL2 (89% identical), mouse Sall2 (89% identical), rat Sall2 (89% identical), pig SALL2 (87% identical), macaque SALL2 (78% identical), dog SALL2 (77% identical), Drosophila melanogaster salm (20% identical), Drosophila melanogaster salr (20% identical), Caenorhabditis elegans sem-4 (14% identical), Caenorhabditis elegans bcl-11 (7% identical), and 1 more. Paralogues in human: SALL3 (31% identical), SALL1 (29% identical), SALL4 (25% identical), HIVEP3 (13% identical), HIVEP1 (12% identical), ZNF536 (12% identical), HIVEP2 (11% identical), ZNF831 (10% identical), BCL11B (10% identical), BCL11A (10% identical), RREB1 (9% identical), ZNF219 (9% identical), and 2 more.
Diseases named in the same sentence as SALL2 in open-access papers:
SALL2 is named in the same sentence as 62 diseases in open-access papers, as found by Europe PMC text mining. Sharing a sentence is not in itself a finding about the gene and the disease. The quoted sentences say what the papers report.
glioblastoma (27 papers, 2015 to 2025). The most malignant astrocytic tumor (WHO grade IV). "Like the glioblastoma context, SALL2 recently was associated with the de-differentiation of breast and melanoma cancer cells into cancer stem cells together with YB-1 and other transcription factors." (PMID 33692826, 2021). "In conclusion, these data are in keeping with METT7LB regulating lineage specification in glioblastoma via epigenetic modulation of the expression of key players, such as SALL2." (PMID 38848215, 2024). "In the nerve system, SALL2 has been identified as stemness factor contributed to the tumorigenesis of glioblastoma." (PMID 39349437, 2024). "In glioblastoma, SALL2 is a core transcription factor of the regulatory network essential for its growth." (PMID 38848215, 2024). "identify METTL7B as an essential regulator of lineage specification and a modulator of the expression of the transcription factor SALL2 with wide-ranging impacts on invasion and tumor growth in glioblastoma." (PMID 38848215, 2024). "Here, we identified METTL7B as an essential regulator of lineage specification and an epigenetic modulator of the expression of the transcription factor SALL2 with wide-ranging impact on invasion and tumor growth in glioblastoma." (PMID 38848215, 2024). "SALL2 is a core transcription factor network component that maintains cancer stemness in glioblastoma, but its role in other cancers, including RMS, is unclear." (PMID 36786012, 2023). "To dissect SALL2 isoform-specific targets, we analyzed publicly available ChIP-seq data from Glioblastoma tumor-propagating cells and in-house ChIP-seq datasets performed in SALL2 wild-type and E1A isoform knockout HEK293 cells." (PMID 33692826, 2021). "An endogenous SALL2 ChIP-seq performed in stem-like tumor-propagating subpopulation from Glioblastoma Multiforme (hereafter MGG8TPC) was included as a binding positive control in this analysis (GEO datasets GSE54047)." (PMID 33692826, 2021). "A subset of only four of them–SOX2, OLIG2, POU3F2, and SALL2–was sufficient to fully reprogram differentiated cells into glioblastoma stem-like cells." (PMID 29773872, 2018). "Interestingly, SALL2 is upregulated in glioblastoma, and together with other neurodevelopmental factors, it promotes glioblastoma propagation, suggesting a dual role for SALL2 in cancer." (PMID 40869218, 2025). "In addition, Sall2 was identified as one of four transcription factors (TFs) reprogramming differentiated glioblastoma cells into stem-like tumor propagating cells (TPCs), suggesting its essential role in neural development and tumor propagation." (PMID 39349437, 2024). "In ovarian cancer, SALL2 is believed to have a role in inhibiting tumor development, but it may promote tumor growth in glioblastoma." (PMID 37946181, 2023). "In addition, high expressions of SALL2 have been found in esophageal cancer, breast cancer, testicular cancer, and glioblastoma." (PMID 36428851, 2022). "Interestingly, the putative tumor suppressor SALL2 was identified as one of the critical transcription factors necessary for maintaining the tumor propagating cells in glioblastoma." (PMID 34944911, 2021). "Moreover, its expression is a recognized marker of the proneural subtype of glioblastomas and, even more importantly, in cooperation with Sox2, Pou3f2 and Sall2, Olig2 is a key master transcription factor of glioblastoma-initiating cells." (PMID 32316617, 2020). "In this sense, there is evidence indicating that SALL2 is involved in stemness, a function that may explain its role in reprogramming differentiated glioblastoma cells into those with ability to propagate a tumor in vivo." (PMID 29689621, 2018). "In glioblastoma, SALL2, together with SOX2, POU3F2, and OLIGO2, reprogrammed differentiated tumor cells into tumor stem cells, and also, SALL2 was one of the partners of SOX2, suggesting SALL2 may be essential for the homeostasis of NSCs in the nervous system in vivo as well." (PMID 39349437, 2024).
glioblastoma (continued). "The critical function of SALL2 in neural differentiation and one of its targets Tuba1a verified in this study may offer potential therapeutic strategy for the diagnosis and treatment of glioblastoma in future." (PMID 39349437, 2024). "Also, we integrated publicly available datasets from glioblastoma MGG8 tumor propagating cells (MGG8TPC) SALL2 ChIP-seq and HEK293 expressing SALL2 short_E1A ChIP-seq (ENCODE Consortium Phase III), and in-house ChIP-seq datasets from SALL2 wild-type and E1A isoform knockout HEK293 cells." (PMID 33692826, 2021). "In neurosphere assays of human glioblastoma cell lines, silencing METTL3 reduces the expression of glioblastoma reprogramming factors POU3F2, SOX2, SALL2, and OLIG2, and inhibits glioblastoma cell proliferation." (PMID 39473440, 2024). "In line with its neural and stem cell renewal function, SALL2, combined with SOX2, POU3F2, and OLIG2 transcription factors, promotes the de-differentiation of glioblastoma cells into stem-like tumor propagating cells." (PMID 33692826, 2021). "In a study conducted on glioblastoma stem cells (GSCs), NOTCH1, SOX2, SALL2, POU3F and OLIG2 blocked differentiation in GSCs, confirming the observations made in GBM by Suvà and colleagues." (PMID 32634370, 2020). "Four core transcription factors (POU3F2, SOX2, SALL2, and OLIG2) are reported to be essential for glioblastoma propagation and sufficient to fully reprogram differentiated glioblastoma cells into glioblastoma stem cells." (PMID 31375149, 2019). "Their expression in differentiated cells strongly correlated with the down-regulation of transcription factors like OLIG2, POU3F2, SALL2, SOX2, capable of reprogramming differentiated glioblastoma cells into stem-like cells." (PMID 29773872, 2018). "The microarray analyses showed significant inverse correlation between SALL2 and CCNE1 mRNA expression in various cancers, including glioblastoma, lymphoma, cervix, pancreas, breast, colon, and lung cancer." (PMID 29689621, 2018). "POU3F2 and other neuro-developmental transcription factors (SOX2, SALL2 and OLIG2) coordinate to play essential roles in the progression of glioblastoma." (PMID 27271588, 2016). "It is also in combination with POU3F2, SALL2, and OLIG2, able to induce glioblastoma tumor growth." (PMID 34021259, 2021). "Here SWIM implicated FOSL1 as a putative master regulator of a core of four master neurodevelopmental transcription factors (i.e., SOX2, SALL2, OLIG2, POU3F2), whose induction was demonstrated to be sufficient to reprogram fully differentiated glioblastoma cells into stem-like cells." (PMID 33785068, 2021). "Importantly, SALL2 regulates the same core of genes in glioblastoma TPC and HEK293 cells, sustaining a conserved network of SALL2 target genes." (PMID 33692826, 2021). "In cancer stem cells, by the induction of a core set of neurodevelopmental transcription factors (POU3F2, SOX2, SALL2, and OLIG2) that are essential for glioblastoma propagation, differentiated glioblastoma cells can be fully reprogrammed into induced stem-like tumor-propagating cells." (PMID 31375149, 2019). "A more recent study has shown that the tumor-propagating potential of glioblastoma cells can be enhanced by increasing the expression of a set of transcription factors normally involved in neuronal development, including POU3F2, SOX2, SALL2 and OLIG2." (PMID 29609590, 2018). "The inhibition of switch genes highly correlates with the activation of genes related to neural development and differentiation, such as the 4-core OLIG2, POU3F2, SALL2, SOX2, whose induction has been shown to be sufficient to reprogram differentiated glioblastoma into stem-like cells." (PMID 30497369, 2018). "A recent study identified four transcription factors (SOX2, SALL2, OLIG2, and POU3F2) as the minimal core sufficient to reprogram differentiated glioblastoma (GBM) cells into stem-like cells." (PMID 34282187, 2021).
glioblastoma (continued). "In glioblastoma multiforme (GBM), a core set of neuro-developmental TFs (POU3F2, SOX2, SALL2, OLIG2) has been identified that was sufficient to reprogram differentiated glioblastoma cells to CSCs." (PMID 33297508, 2020).
glioma (16 papers, 2017 to 2024). A benign or malignant brain and spinal cord tumor that arises from glial cells (astrocytes, oligodendrocytes, ependymal cells). "SOX1 expression was low in Sall2 KO cells during neural differentiation, and SALL2 was one of the factors that can reprogram differentiated glioma cells into glioma stem cells." (PMID 39349437, 2024). "For example, SALL2 is a tumor suppressor in ovarian cancers but promotes aggressiveness in the glioma context." (PMID 36438565, 2022). "On the other hand, in the glioma context, SALL2 and SALL4 are upregulated, potentially exerting a synergistic effect on the regulation of integrin β1." (PMID 36438565, 2022). "More importantly, Olig2 protein is synergistic with Sox2, Pou3f2 and Sall2 and is a key transcription factor of glioma initiating cells." (PMID 32943100, 2020). "Consistent with NS-culture-derived glioma cells with high invasiveness, genes highly expressed in 51A were those encoding markers of neural stem/precursor cells (NANOG, POU3F2, POU5F1, and SALL2), and pro-invasive proteins (AGAP2, EPHA2, FOXM1, PDGFRA, and TNC)." (PMID 29113349, 2017). "METTL3 silencing reduced the expression of the glioma reprogramming factors POU3F2, SOX2, SALL2 and OLIG2, and suppressed GSC proliferation in neurosphere assays derived from human glioma cell lines." (PMID 37444417, 2023). "METTL3 is also upregulated in glioblastoma, and silence of METTL3 inhibits the growth of glioma stem cells by downregulating POU3F2, SOX2, SALL2, OLIG2, and other glioma recombinant factors." (PMID 35571490, 2022). "The change in m6A modification and the transcript level of four glioma reprogramming factors (SOX2, SALL2, OLIG2 and POU3F2) and selected transcripts were validated by m6A RIP-PCR and RT-qPCR." (PMID 30781903, 2019). "IMP3 silencing also resulted in the downregulation of four glioma reprogramming transcription factors- OLIG2, POU3F2, SOX2 and SALL2 in GSCs." (PMID 28465487, 2017). "Expanding our analyses to glioma samples in TCGA, we observed significant negative correlations for SALL2, WNT3, and SEMA5B with METTL7B expression." (PMID 38848215, 2024). "Indeed, POU3F2, SOX2, SALL2, and OLIG2 have been shown to be the core set of transcription factors essential for GBM propagation, which are within the set of 19 transcription factors (including SOX1) required for successful reprogramming of differentiated glioma cells into GSCs48." (PMID 28425506, 2017).
breast carcinoma (15 papers, 2017 to 2024). "SALL2 downregulation leads to loss of sensitivity to hormone therapy in breast cancer patients, affecting cell proliferation and apoptosis." (PMID 37946181, 2023). "The hypermethylation of the SALL2 promoter was associated with aggressive and tamoxifen-resistant breast cancer phenotypes." (PMID 34944911, 2021). "We further evaluated the effect of SALL2 loss on estrogen‐independent and tamoxifen‐resistant phenotype in breast cancer cells in vivo." (PMID 31657150, 2019). "Taken together, these results indicate that lower SALL2 could potentially predict higher risk of metastatic relapse and poorer prognosis in ER+ breast cancer patients treated with tamoxifen therapy." (PMID 31657150, 2019). "MDA-MB-231 human breast cancer cells exhibited a transient increase in SALL2 protein levels under Silmitasertib treatment." (PMID 38493149, 2024). "Epigenetic regulation of SALL2 has been described; hypermethylation of its promoter was found to contribute to the acquisition of tamoxifen resistance in breast cancer." (PMID 38848215, 2024). "It has been demonstrated that epigenetic silencing of Spalt-like transcription factor 2 (SALL2) contributes to tamoxifen resistance in breast cancer by activating the AKT/mTOR pathway." (PMID 36890838, 2023). "Studies in breast cancer cells demonstrate that SALL2 silencing induced the AKT/mTOR pathway activation via the downregulation of PTEN." (PMID 36438565, 2022). "Treatment with 5-Aza-dC, a DNMT inhibitor, increased the sensitivity of SALL2 hypermethylated breast cancer to tamoxifen therapy in vitro and in vivo." (PMID 34944911, 2021). "In breast cancer cells, SALL2 silencing activated the AKT/mTOR pathway via the downregulation of PTEN." (PMID 34944911, 2021). "Of relevance here is 5-azacitidine, a DNMTi (DNA methyltransferase inhibitor), which triggered SALL2 restoration and sensitized tamoxifen-resistant breast cancer to tamoxifen therapy in vivo." (PMID 34944911, 2021). "For instance, associated with their tumor suppressor role, the hypermethylation of the SALL1 and SALL2 promoters were described in breast cancer and esophageal squamous cell carcinoma (ESCC)." (PMID 34944911, 2021). "More importantly, MYB and SALL2 were suggested to attenuate histological grade promotion and prevent breast cancer progression." (PMID 34944911, 2021). "In contrast to HIF-1α, Spalt-like transcription factor 2 (SALL2), a transcription factor related to disease progression, enhances the sensitivity of breast cancer cells to tamoxifen, while ERα is downregulated after silencing SALL2." (PMID 33362547, 2020). "Hypermethylated SALL2 is found in the TAM-resistant ER+ TAMR/MCF-7 breast cancer cell line, which leads to SALL2 downregulation." (PMID 32850327, 2020). "Taken together, these results suggest that SALL2 expression correlates with response to tamoxifen therapy in breast cancer." (PMID 31657150, 2019). "Altogether, these results indicate that promoter hypermethylation mediates SALL2 downregulation in tamoxifen‐resistant breast cancer." (PMID 31657150, 2019). "The positive correlation between SALL2 expression and better prognosis was also significant in tamoxifen‐treated ER+ breast cancer patients." (PMID 31657150, 2019). "We next examined the effect of DNMT inhibitor on tamoxifen sensitivity in SALL2‐hypermethylated breast cancer cells in an in vivo mouse model." (PMID 31657150, 2019). "Analysis of the collected breast cancer tissues and of a TCGA breast cancer dataset revealed that only the E1A isoform of SALL2 was expressed in breast cancer samples." (PMID 31657150, 2019). "In vivo experiments revealed that restoration of SALL2 using DNA methyltransferase (DNMT) inhibitor resensitized tamoxifen‐resistant breast cancer to tamoxifen therapy." (PMID 31657150, 2019). "Recently, SALL2 was found to be downregulated in several human cancer types, including breast cancer, ovarian cancer, and esophageal squamous cell carcinoma." (PMID 31657150, 2019).